YTHDF1 (YTH N6-methyladenosine RNA binding protein F1)
Diseases named in the same sentence as YTHDF1 in open-access papers (continued):
Sharing a sentence is not in itself a finding about the gene and the disease.
melanoma (continued). "In melanoma, m6A-marked mRNAs regulate neoantigen-specific immunity through YTH N6-Methyladenosine RNA Binding Protein 1 (YTHDF1) present in DCs." (PMID 39000359, 2024). "Several m6A regulators including METTL3, YTHDF1, HNRNPA2B1, FTO, and IGF2BP3 are involved in melanoma." (PMID 37124930, 2023). "The study showed that 15 genes were changed on mRNA expression and m6A regulatory proteins such as RBM15, YTHDF1, WTAP, and METTL14 genes in melanoma with a higher degree of genomic variation and a worse prognosis." (PMID 37124930, 2023). "In GEO datasets, except YTHDC2, other m6A readers like YTHDF1, YTHDF2, YTHDF3 and YTHDC1 have a significant higher expression in melanoma tissues." (PMID 36324258, 2022). "One systematic analysis revealed that the expressions of YTHDF1 and HNRNPA2B1 were upregulated in melanoma." (PMID 34105069, 2021). "All tested MCC cell lines indicated higher expression level of YTHDF1 and YTHDF2 compared to the tested melanoma cell lines." (PMID 31947544, 2020). "To evaluate gene copy numbers, we designed fluorescent probes to detect YTHDF1 and performed fluorescent in situ hybridization in six MCC cell lines, two melanoma cell lines, and normal diploid control cells (fibroblasts)." (PMID 31947544, 2020). "YTHDF1 and HNRNPA2B1 were significantly over-expressed in patients with melanoma while ELF3 was down-regulated." (PMID 32549786, 2020). "Comparing primary melanoma and metastases, we found that ALKBH5, ELAVL1, FMR1, HNRNPA2B1, HNRNPC, IGF2BP1/2/3, KIAA1429, LRPPRC, RBM15, YTHDC1/2, YTHDF1/3, and ZC3H13 were significantly upregulated in metastases, while RBM15B and METTL3 were significantly upregulated in primary melanoma." (PMID 34993195, 2021). "The results revealed the up-regulation of YTHDF1 and HNRNPA2B1 in melanoma." (PMID 32549786, 2020). "We further examined whether the combination of YTHDF1 and HNRNPA2B1 had higher efficacy in diagnosing melanoma by using linear regression and found the efficacy was improved from about 0.760 to 0.857 (P < 0.0001)." (PMID 32549786, 2020). "All the genes in the identified pathways were also positively related to YTHDF1 or HNRNPA2B1, suggesting the expression of both genes might influence m6A modifications in mRNA genes and potentially result in melanoma heterogeneity at the cellular level." (PMID 32549786, 2020). "YTHDF1 might negatively regulate STAT1 and further facilitated melanoma development, but the roles of STAT1 and CD86 in the general network were not large enough to mitigate the trend of disease development." (PMID 32549786, 2020). "Statistical analysis revealed the significance of YTHDF1 and HNRNPA2B1 and the combination of the two genes may provide a better approach to diagnose melanoma." (PMID 32549786, 2020). "Although in normal melanoma, the other family member YTHDF1 does not reduce cell proliferation and migration, it can promote translation of the histidine triad nucleotide-binding protein 2 tumor suppressor in ocular melanoma, being shown to promote tumor regression in vitro and in vivo." (PMID 34105069, 2021). "To investigate whether this finding that can distinguish MCC from other skin cancers can be recapitulated in tumor sample biopsies from MCC patients, we performed YTHDF1 immunohistochemistry on tissue microarrays (TMAs) consisting of 31 MCC patients and 26 melanoma patients." (PMID 31947544, 2020).
melanoma (continued). "Moreover, YTHDF1 or HNRNPA2B1 might interact with RNA processing-related genes such as CDK1/CDK2 and further promote the formation and progression of melanoma." (PMID 32549786, 2020).
glioma (30 papers, 2019 to 2025). A benign or malignant brain and spinal cord tumor that arises from glial cells (astrocytes, oligodendrocytes, ependymal cells). "The concomitant upregulation of MSI1 and YTHDF1 was associated with decreased survival of glioma patients." (PMID 33317545, 2020). "In summary, our study showed that YTHDF1 is associated with glioma progression, and high YTHDF1 expression also predicts a poor prognosis in glioma patients." (PMID 32449290, 2020). "MSI1and YTHDF1 were shown to be positively correlated in clinical glioma samples,and their concomitant upregulation was associated with decreased survival ofglioma patients." (PMID 33317545, 2020). "The results of these studies are consistent with our findings that the high expression of YTHDF1 in glioma is associated with worse OS and advanced stages." (PMID 32449290, 2020). "Similarly, expression of the YTHDF1 paralog is negatively associated with survival and promotes glioma cell proliferation and growth in vitro." (PMID 36831575, 2023). "The high expression of YTHDF1 in glioma was associated with worse OS (P < 0.05)." (PMID 32449290, 2020). "Furthermore, glioma patients with YTHDF1 mutations have a better overall survival and disease‐free survival than those of the wild‐type." (PMID 32449290, 2020). "In addition, the low YTHDF1 levels in glioma cells were associated with low tumour growth rates and smaller tumour weight, whereas the high YTHDF1 levels in glioma cells were associated with higher tumour growth rates and tumour weight." (PMID 32449290, 2020). "Similarly, up-regulation of YTHDF1 is positively associated with advanced tumor grade of glioma." (PMID 36650570, 2023). "Interestingly, the OS and DFS of the YTHDF1 mutations in glioma were performed via the cBioPortal." (PMID 32449290, 2020). "Mechanistic studies have revealed that cellular myelocytomatosis viral oncogene homolog (C-MYC), as a key regulator, strongly enhances glioma cell growth and spread via the YTH domain-containing family protein 1 (YTHDF1)-regulated FDX1 methylation mechanism." (PMID 41463095, 2025). "further highlighted that the FDX1 expression is promoted by the c-Myc-YTHDF1 signaling pathway in glioma cells and demonstrated that the c-Myc-YTHDF1/FDX1 axis inhibited the mitophagy and promoted the malignant phenotype of glioma cells." (PMID 38918694, 2024). "YTHDF1 has been shown to predict poor prognosis in glioma patients, and the knockdown of YTHDF1 in GBM inhibits proliferation and reduces resistance to temozolomide in both patient-derived cell lines and xenograft models." (PMID 37444417, 2023). "A similar risk signature (ALKBH5, IGF2BP2, IGF2BP3, HNRNPA2B1, YTHDF1, YTHDF2, RBM15, and WTAP) was shown to be prognostic for glioma patients, and the expression of IGF2BP2 and IGF2BP3 was linked to tumour occurrence, development, and progression." (PMID 36831575, 2023). "Studies have shown that YTHDF1 is upregulated in gliomas and is positively correlated with patient age and tumor grade." (PMID 37964279, 2023). "In one study, Xu and his colleagues analysed the abnormal expression of the m6A regulatory factor in gliomas and screened the YTHDF1 factor according to its impact on the survival and prognosis of gliomas." (PMID 35688823, 2022). "This study identified has-mir-346 as an upstream regulator of YTHDF1 to participate in the development of glioma." (PMID 35625706, 2022). "In our investigation, univariate analysis revealed that ages, grade, stage and YTHDF1 expression were statistically significant factors for glioma progression." (PMID 32449290, 2020). "To further study the biological significance of YTHDF1 in gliomas, we injected U87‐siYTHDF1 and SHG‐44‐pcYTHDF1 cells and their corresponding controls subcutaneously in nude mice and monitored their tumour growth." (PMID 32449290, 2020).
glioma (continued). "The results of the multivariate analysis revealed that the dimension, subtype, age, grade, stage and YTHDF1 were statistically significant factors for glioma progression." (PMID 32449290, 2020). "First, RT‐qPCR assay was performed to investigate the expression of YTHDF1 in different glioma cells." (PMID 32449290, 2020). "Taken together, our analysis on the online public database reveal a potential significant involvement of YTHDF1 in brain and CNS cancer." (PMID 33317545, 2020). "There are several independent interaction groups in ‘readers’, suggesting the diverse functions of different ‘readers’, but the expressions of YTHDF2, YTHDC2 and YTHDF1 were significantly correlated with each other in gliomas." (PMID 30810537, 2019). "Studies have confirmed that high expression of YTHDF1 predicts a poor prognosis in glioma patients." (PMID 40469294, 2025). "Additionally, YTHDF1 plays a role in RNA editing, as it binds and promotes the translation of m6A-modified ADAR1, a molecule implicated in glioma progression." (PMID 38474421, 2024). "Notably, the microRNA hsa-mir-346 exhibits the ability to bind to the 3′UTR of YTHDF1, leading to the negative regulation of YTHDF1 expression in glioma cells." (PMID 38398118, 2024). "YTHDF1 is involved in various mechanisms that contribute to glioma resistance and progression." (PMID 38474421, 2024). "has-mir-346 was found to regulate and bind to the 3′-UTR of YTHDF1 in glioma cells." (PMID 37964279, 2023). "The expression of YTHDF1 is positively related to a poor prognosis in glioma patients." (PMID 38072944, 2023). "Notably, YTHDF1 knockdown increased the sensitivity of glioma cells to the antiproliferative effects of TMZ, demonstrating its potential as a synergistic target for improved treatment response in GBM." (PMID 36831575, 2023). "In addition, the Cox regression algorithm has been used to analyze 11 related prognostic genes, including ALKBH5, YTHDF1, YTHDF2, and HNRNPC in the CGGA to predict risk scores in glioma patients." (PMID 38072944, 2023). "In addition, they also found that miR-3436 can negatively regulate YTHDF1, which is related to the poor prognosis of glioma patients." (PMID 35688823, 2022). "Notably, m6A writers METTL3, METTL16, and KIAA1429 exhibited a cross-talk with the m6A reader YTHDF1 in gliomas, GBM, and LGG." (PMID 34589481, 2021). "YTHDF1 and 78 targets involved the occurrence of glioma and GBM, not LGG, among which 181 genes were associated with overall survival." (PMID 34589481, 2021). "In conclusion, m6A RNA methylation regulators KIAA1429, METTL16, METTL3, IGF2BP2, and YTHDF1, as well as their targets may play a critical role in the occurrence of glioma, which may be beneficial to therapeutic customization and clinical decision-making." (PMID 34589481, 2021). "YTHDF1 and 78 targets involved the occurrence of glioma and GBM." (PMID 34589481, 2021). "MSI1 and YTHDF1 demonstrated mildly positive correlation of expression in glioma datasets." (PMID 33317545, 2020). "Although this experiment was performed in human cervical cancer HeLa cells, unique regulation of separate mRNAs by YTHDF1 versus YTHDF2 in gliomas could provide an intriguing explanation for overexpression of both genes in high grade gliomas." (PMID 32375856, 2020). "Taken together, these data suggest that YTHDF1 promotes the growth of glioma tumours in vivo." (PMID 32449290, 2020). "Moreover, YTHDF1 was the most specifically expressed in brain and CNS cancers comparing to other types of tumors." (PMID 33317545, 2020). "Similarly, miR-343 is involved in the regulation of YTHDF1 expression in glioma." (PMID 36650570, 2023). "However, there is limited research on the role of YTHDF1 and eIF3 in glioma." (PMID 38072944, 2023). "YTHDF1 may have an essential function in glioma diagnosis, treatment and prognosis." (PMID 32449290, 2020).
glioma (continued). "Finally, we identified hsa‐mir‐346 as an upstream regulator of YTHDF1 expression, which may be involved in the development of a new treatment reducing the development of glioma." (PMID 32449290, 2020). "The results showed that METTL14, FTO, YTHDF1, and YTHDF3 demonstrated significant upregulation in low-grade gliomas compared to normal tissues." (PMID 38398118, 2024). "Another approach to sensitise glioma cells to treatment was explored by modulating m6A ‘reader’ and member of the YTH protein family, YTHDF1." (PMID 36831575, 2023). "A more recent study has shown, using both glioma cell lines and mouse models, that METTL3 methylates ADAR1 mRNA which, mediated by YTHDF1, led to its increased expression at the protein level." (PMID 37444417, 2023). "Previous studies have shown that YTHDF1, YTHDF2, IMP2 and hnRNPA2B1 are highly expressed in gliomas, while hnRNPC is poorly expressed in gliomas." (PMID 35688823, 2022). "Recently, another study also analyzed the correlation of m6A regulators and prognostic features and found that HNRNPC, WTAP, YTHDF1, and YTHDF2 were significantly upregulated in glioma tumors in patients with good OS." (PMID 34381710, 2021). "Studies have shown that YTHDF1 and YTHDF2 mRNA expression levels are positively correlated with malignancy of gliomas, with significant increases in higher grade gliomas, suggesting a role for these m6A readers in glioma progression." (PMID 33718165, 2021). "The differential analysis showed that ALKBH1, TRMT6, TRMT10C, YTHDF1, and YTHDF2 were significantly overexpressed in high-grade gliomas." (PMID 34631793, 2021). "We found that ALKBH1, TRMT6, TRMT10C, YTHDF1, and YTHDF2 were significantly overexpressed in high-grade gliomas and the expression of TRMT6 and YTHDF2 was higher in IDH wild-type patients." (PMID 34631793, 2021). "For glioma, we found that IGF2BP2, KIAA1429, METTL16, METTL3, and YTHDF1 are consistently upregulated at the mRNA level of CGGA and GSE16011 datasets (7.97E-05 < FDR < 0.04)." (PMID 34589481, 2021). "In glioma research, a bioinformatics analysis in the CGGA microarray and RNA sequencing databases showed that the levels of YTHDC2, YTHDF1, YTHDF2, and YTHDF3 were elevated in gliomas." (PMID 34721530, 2021). "For the m6A methylation readers, the expression of HNRNPC, YTHDF1, and YTHDF2 was significantly increased in high-grade gliomas." (PMID 30810537, 2019). "In the intricate network of glioma pathogenesis, the YTHDF family, consisting of YTHDF1, YTHDF2, and YTHDF3, and YTHDC1 and YTHDC2, as members of the YTH domain-containing family, play significant roles in the prognosis and molecular mechanisms underlying glioma." (PMID 38474421, 2024). "Abnormally high expression of YTHDF1 is also correlated with poor survival in patients with glioma, and research has shown that YTHDF1 accelerates glioma growth, while microRNA has-mir-3436 binds to the 3′ UTR region of YTHDF1 and negatively regulates YTHDF1." (PMID 38102645, 2023). "Among the proteins with YTH domains, YTHDF1, YTHDF2, and YTHDF3 play pivotal roles in gliomas." (PMID 37964279, 2023). "Moreover, the expressions of WTAP, RBM15, YTHDF2, YTHDF1 and ALKBH5 were highly correlated with each other, and all of their expressions were negatively correlated with FTO in gliomas." (PMID 30810537, 2019). "YTHDF1 and 78 targets involved the occurrence of glioma and GBM, not LGG." (PMID 34589481, 2021). "MSI1 and YTHDF1 can be considered as negative prognostic markers in gliomas." (PMID 33317545, 2020). "To summarize, MSI1 and YTHDF1 can be considered as negative prognostic markers in gliomas." (PMID 33317545, 2020). "As is visible in the violin plot, the mRNA expression levels of YTHDF2, YTHDF1, METTL3, RBM15 and HNRNPC were up‐regulated in glioma compared to normal tissues, whereas the expression levels of ALKBH5, WTAP, YTHDC2, ZC3H13 and METTL14, especially of FTO, were decreased in glioma." (PMID 32449290, 2020).
lung adenocarcinoma (25 papers, 2014 to 2025). A carcinoma that arises from the lung and is characterized by the presence of malignant glandular epithelial cells. "In lung adenocarcinoma, the low YTHDF1 group was mainly enriched in immunity-related signaling pathways (allograft rejection, IL6-JAK-STAT3 signaling, inflammatory response, and IL2-STAT5 signaling)." (PMID 36479088, 2022). "In lung adenocarcinoma, YTHDF1 is significantly negatively correlated with PD-L1, PD-1, PD-L2, CTLA-4, TIGIT, VISTA, and TIM3." (PMID 36479088, 2022). "YTHDF1 has an immune hot profile in both lung adenocarcinoma and squamous cell carcinoma, whereas YTHDF2 is only seen in adenocarcinoma." (PMID 36479088, 2022). "Compared with the control group, METTL3 and YTHDF1 are overexpressed in patients with lung adenocarcinoma, and the YTHDF2 is overexpressed in most cases." (PMID 34489709, 2021). "Especially, it has been demonstrated that several m6A methyltransferase, such as METTL3 and YTHDF1, facilitate lung adenocarcinoma progression by activating cell migration and invasion through m6A methylation." (PMID 33193582, 2020). "Collectively, H2S impedes ATTM-induced anticancer effects through YTHDF1-dependent PRPF6 m6A methylation in lung adenocarcinoma cells." (PMID 32195181, 2020). "In the present study, ATTM was found to promote cell growth, proliferation and invasion in lung adenocarcinoma cells, through YTHDF1-dependent PRPF6 m6A methylation." (PMID 32195181, 2020). "We show that YTHDF1 deficiency inhibits NSCLC cell proliferation and xenograft tumor formation through regulating the translational efficiency of CDK2, CDK4, and cyclin D1, and that YTHDF1 depletion restrains de novo lung adenocarcinomas (ADC) progression." (PMID 31653849, 2019). "For instance, in lung adenocarcinoma, high HNRNPC and IGF2BP3 levels correlate with reduced overall survival, and a six-gene risk signature (KIAA1429, ALKBH5, METTL3, HNRNPC, YTHDC2, and YTHDF1) strongly correlated with various clinical and pathological features." (PMID 36831575, 2023). "The combination of YTHDF1, a m6A “reader”, with methylated ENO1 mRNA leads to increased expression of ENO1 and promotes glycolysis of lung adenocarcinoma." (PMID 37582735, 2023). "A further study also identified METTL3, YTHDF1, and YTHDF2 as prognostic lung adenocarcinoma biomarkers." (PMID 36831575, 2023). "For example, in lung adenocarcinoma (LUAD) cells, elevated lncRNA LINC00337 expression significantly promotes YTHDF1 expression by sponging the miR-1285-3p thus promoting LUAD cells proliferation and metastasis." (PMID 36650570, 2023). "This can increase the modification of m6A in c-MYC mRNA and recruit YTHDF1 to promote the translation of c-MYC mRNA, ultimately accelerating the glycolysis and proliferation of lung adenocarcinoma cells." (PMID 37582735, 2023). "The YTHDF1 inhibitor GB1107 was also proven to inhibit the growth and metastasis of lung adenocarcinoma in vivo." (PMID 34026603, 2021). "Data from The Cancer Genome Atlas (TCGA) and Genotype-Tissue Expression (GTEx) database show that both YTHDF1 and YTHDF2 were highly expressed in lung adenocarcinoma." (PMID 33692959, 2021). "Among these genes, KIAA1429, HNRNPC, YTHDC2, METTL3, WTAP, YTHDC1, and FTO were down expressed in lung adenocarcinoma, RBM15, ZC3H13, YTHDF1, YTHDF2, and ALKBH5 were up expressed." (PMID 32398949, 2020). "Overall, our study revealed that the YTHDF1–m6A–FTH axis participates in the progression of lung adenocarcinoma, suggesting the pathway axis might be a novel therapeutic target for lung adenocarcinoma treatment." (PMID 37259333, 2023).